MYD88 (MYD88 innate immune signal transduction adaptor)
Diseases named in the same sentence as MYD88 in open-access papers (continued):
Sharing a sentence is not in itself a finding about the gene and the disease.
primary cutaneous diffuse large B-cell lymphoma, Leg type (1 paper, 2018). An aggressive primary cutaneous B-cell lymphoma, usually involving the lower leg. "Primary cutaneous diffuse large B-cell lymphoma, leg type (PCDLBCL-LT) is one of the well-recognized extranodal lymphomas commonly addicted to the B-cell receptor-MYD88 superpathway." (PMID 29899297, 2018).
prion disease (1 paper, 2012). A transmissible disease that is caused by a protein that is able to induce abnormal folding of normal cellular proteins, leading to characteristic spongiform brain changes, which are associated with neuronal loss without an inflammatory response. "Investigation into whether TLR2 signaling is indeed important in prion disease pathology, and the identification of signaling pathways important in microglial activation independent of MyD88, warrants further investigation." (PMID 22363497, 2012).
pyometra (1 paper, 2016). "Constitutive transcription of MyD88-dependent (MyD88, TRAF6, NFKβ) and independent (TRAM, TRIF, IRF3) pathway components was detected in healthy diestrous and pyometra endometria." (PMID 27829462, 2016).
renovascular hypertensive (1 paper, 2019). "This suggests that 8 weeks of aerobic ExT may decrease blood pressure in hypertensive rats by reducing the PICs activation through TLR4/MyD88/NF-κB signaling within the PVN, and thus delays the progression of 2K1C renovascular hypertension." (PMID 31708733, 2019). "Thus, to reveal the upstream signaling events that lead to decreased PICs production in the PVN following ExT, we tested the hypothesis that ExT can suppress TLR4/MyD88/NF-κB signaling in the PVN and thus attenuate two-kidney-one-clip (2K1C) renovascular hypertension." (PMID 31708733, 2019).
retinal disease (1 paper, 2021). "Myeloid differentiation primary response protein 88 (MyD88) is a central adaptor protein for innate immune system Toll‐like receptors (TLR) and induces cytokine secretion during retinal disease." (PMID 34562309, 2021).
retinal ischemia (1 paper, 2014). A ischemic disease that involves the retina. "To evaluate the effects of the Myd88-dependent and Trif-dependent signaling cascades on the severity of retinal ischemia, we used Myd88KO and TrifKO mice." (PMID 24754835, 2014).
rhinosinusitis (1 paper, 2022). "Nevertheless, a massive rhinosinusitis and catarrh accompanied by accumulation of mucopurulent exudate still developed in the nasal cavity of the immunodeficient MyD88 KO mice at the peak of infection, once a human-like high bacterial colonization level was reached." (PMID 35395059, 2022). "We used immunodeficient C57BL/6J MyD88 KO mice to achieve B. pertussis proliferation to human-like high counts of 108 viable bacteria per nasal cavity to elicit rhinosinusitis accompanied by robust shedding and transmission of B. pertussis bacteria to adult co-housed MyD88 KO mice." (PMID 35395059, 2022).
Rickettsia infection (1 paper, 2022). "There is also interplay between autophagy and inflammatory pathways during both Ehrlichia and Rickettsia infection, and autophagy induction is balanced by signaling of MyD88 (a downstream adaptor for many pattern recognition receptors) during ehrlichial infection." (PMID 35155277, 2022).
salmonellosis (1 paper, 2012). Infections with bacteria of the genus salmonella. "At later time points, substantial neutrophil infiltration was observed even in mice deficient in MyD88 or TLR4 suggesting that multiple partially redundant pathways triggered neutrophil infiltration at high Salmonella loads in agreement with previous data for systemic salmonellosis." (PMID 22586458, 2012).
Schnitzler syndrome (1 paper, 2023). A rare, underdiagnosed disorder in adults characterized by recurrent febrile rash, bone and/or joint pain, enlarged lymph nodes, fatigue, a monoclonal IgM component, leukocytosis and systemic inflammatory response. "Schnitzler’s syndrome is a rare adult-onset autoinflammatory disease that invovles both hematological and rheumatological features, and 90% of patients with Schnitzler’s syndrome who also develop macroglobulinemia carry a somatic mutation in the Toll-like receptor adapter MYD88." (PMID 36585519, 2023).
Seizure (1 paper, 2016). A seizure is an intermittent abnormality of nervous system physiology characterized by a transient occurrence of signs and/or symptoms due to abnormal excessive or synchronous neuronal activity in the brain. "Seizure-induced TLR4/MYD88 signaling plays a critical role in activating microglia and triggering neuron apoptosis." (PMID 27193049, 2016).
seminoma (1 paper, 2025). A radiosensitive malignant germ cell tumor found in the testis (especially undescended), and extragonadal sites (anterior mediastinum and pineal gland). "In seminoma, hsa-miR-138-5p emerged as a master regulator by targeting hub gene such as MYD88, thereby modulating apoptosis, immune signaling, and cell-cycle pathways." (PMID 40869426, 2025). "A direct interaction between MYD88 and hsa-miR-138-5p has been experimentally validated in miRDB, confirming the regulatory role of this miRNA in seminoma." (PMID 40869426, 2025). "Although miR-138-5p and miR-200b-3p have been previously implicated in regulating oncogenes like MYD88 and CDK1 in various cancers, our study provides the first comprehensive analysis of these miRNAs in seminoma and teratoma." (PMID 40869426, 2025).
serous carcinomas (1 paper, 2014). "While 73% (62/85) of malignant tumours were TLR4 positive (mixed subtypes), co-expression of MyD88 was observed in only 47% cases, which were all serous carcinomas." (PMID 24977712, 2014). "However in this study, TLR4/MyD88 co-expression showed a predilection for serous neoplasms in general, particularly borderline and malignant serous tumours, and was expressed in both high- and low-grade serous carcinomas." (PMID 24977712, 2014). "TLR4 expression was present in all ovarian epithelium (normal and neoplastic), whereas MyD88 was restricted to neoplastic cells, independent of tumour grade and associated with reduced progression-free and overall survival, in an immunohistological specific subset of serous carcinomas, p<0.05." (PMID 24977712, 2014). "In contrast TLR4 in the absence of MyD88 was associated with non-malignant tissue, non-serous benign and borderline tumours, a subgroup of serous carcinomas and non-serous carcinomas (MyD88 negative EOC)." (PMID 24977712, 2014). "All non-serous carcinomas (mucinous, clear cell and endometrioid) were MyD88 negative." (PMID 24977712, 2014). "Cases excluded from follow-up included non-serous carcinomas (all MyD88 negative), those with recurrent disease (n = 2), patients who died of post-operative complications or unrelated causes (n = 2) and patients lost to follow-up (further treatment and follow-up at a different institution)." (PMID 24977712, 2014).
serous neoplasm (1 paper, 2014). "The expression of both TLR4 and MyD88 was most uniform and strongest in serous neoplasms, particularly borderline and malignant serous tumours." (PMID 24977712, 2014).
signet ring cell carcinoma (1 paper, 2016). A usually aggressive, poorly differentiated invasive adenocarcinoma characterized by the presence of malignant glandular cells in which the nucleus is pressed to one side by the presence of intracytoplasmic mucus. "Therefore, we hypothesize that, in our patient, the partial MYD88 defect causes an impaired immune response, resulting in recurrent C. albicans infections and nonspecific gastritis increasing the risk of signet ring cell carcinoma of the stomach wall." (PMID 26700889, 2016).
spinocerebellar ataxia type 6 (1 paper, 2017). Spinocerebellar ataxia type 6 (SCA6) is the most common subtype of autosomal dominant cerebellar ataxia type III (ADCA type III) characterized by late-onset and slowly progressive gait ataxia and other cerebellar signs such as impaired muscle coordination and nystagmus. "In favour of this hypothesis, genetic inactivation of Myd88, a critical signal transduction component in TLR signalling and important for downstream IKK/NF-κB activation, alters neuroinflammation and attenuates Purkinje cell loss in a spinocerebellar ataxia type 6 mouse model." (PMID 28193238, 2017).
streptococcal infection (1 paper, 2014). Any of the several infectious disorders caused by members of streptococcus, a genus of gram positive bacteria belonging to the family Streptococcaceae. "For instance, mouse dendritic cell maturation and cytokine production in response to GAS is entirely MyD88-dependent, indicating the important role of the innate immunity in streptococcal infection." (PMID 24499202, 2014).
tendinitis (1 paper, 2024). Inflammation of a tendon, usually resulting from an overuse injury. "The qPCR results showed that CD36 and MYD88 were significantly elevated in patients with tendinitis compared to healthy controls." (PMID 38919626, 2024). "This suggests that in tendinitis, there is an elevated T-independent B cell response, primarily mediated by Toll-like receptors (TLRs) and MYD88." (PMID 38919626, 2024). "Additionally, our study highlights key molecular pathways, immune cells, and transcription factors involved in tendinitis, such as the roles of MYD88, CD36, CREB5, and ELF4." (PMID 38919626, 2024). "The predominance of this pathway underscores the critical role of innate immunity in tendinitis, highlighting how the interaction between TLRs and MYD88 facilitates a rapid immune response independent of T cell help." (PMID 38919626, 2024).
thrombosis (1 paper, 2018). "HMGB1 was associated with thrombosis in patients with AF via the MyD88/NFκB pathway after adjustment for cardiac and extra cardiac inflammation variables." (PMID 29595637, 2018).
tuberculous meningitis (1 paper, 2022). "Treatment with dexamethasone was found to significantly reduce TLR4 and MyD88 expression in monocytes derived from patients with tuberculous meningitis (TBM)." (PMID 36505429, 2022).
Ureaplasma infection (1 paper, 2013). "Furthermore, when we investigated whether TLR9 was triggering signalling from the endosomes in response to Ureaplasma infection, it was shown that following Ureaplasma infection, TLR9 co-localised in the endosomes with the signalling adaptor molecule MyD88." (PMID 23593431, 2013).
viral pneumonia (1 paper, 2018). Inflammation of the lung parenchyma that is caused by a viral infection. "In the present study, we find that OMT can significantly decrease the expressions of TLR3, TLR4, TLR7, MyD88, and TRAF6 genes after IAV infection, and we preliminarily speculate that OMT may inhibit IAV proliferation and IAV viral pneumonia via inhibiting TLRs signaling pathways." (PMID 29570670, 2018).
vitamin A deficiency (1 paper, 2017). Deficiency of vitamin A due to malnutrition, malabsorption, or dietary lack. "For example, vitamin A deficiency causes perturbations in the gut microbiota by reducing the ratio of Firmicutes and Proteobacteria on a Myd88- and TRIF-dependent manner." (PMID 28458670, 2017).
Yersinia infection (1 paper, 2025). "However, those with a normal BMI should be cautious to prevent Yersinia infection, since MAP2K1, PLCG1, and MYD88 exhibit mutual exclusivity and are significantly enriched in this pathway." (PMID 40768543, 2025).
infection (746 papers, 2006 to 2026). The state of being infected such as from the introduction of a foreign agent such as serum, vaccine, antigenic substance or organism. "Following infection with Hp, these MyD88-deficient mice developed gastric mucosal atrophy, intestinal metaplasia, and dysplasia at both 25 and 47 weeks post-infection, thereby highlighting the importance of immune signaling in gastric carcinogenesis." (PMID 40673273, 2025). "Myd88-deficiency attenuated secretion of IL-6 and TNFα upon infection with CFT073, while tlr4-deficiency almost completely abolished secretion of both cytokines." (PMID 41310197, 2025). "It should also be noted that a slight infection defect was observed in MyD88-deficient BMDMs, which likely contributed to the decreased F. tularensis transfer (data not shown)." (PMID 40313956, 2025). "Although 3d mice survived longer than MyD88-deficient mice, they ultimately succumbed early during the infection, showing similar susceptibility to K. pneumoniae as TLR4-deficient mice." (PMID 40248691, 2025). "Mice lacking Nod2 (Nucleotide-binding oligomerization domain-containing protein 2), Myd88 (Myeloid differentiation primary response protein), and Tlr2 (Toll-like receptor 2) are more susceptible to infection with S. aureus than mice expressing these genes." (PMID 39178306, 2024). "Globally, MyD88/IRAK-4–deficient patients were less likely to develop severe infections (mild infections: 27.3 vs. 5.7%; moderate: 27.3 vs. 2.9%; severe: 18.2 vs. 11.4%; critical: 27.3 vs. 80%; P = 0.0002)." (PMID 36880831, 2023). "Further, the protective role of MyD88 in ehrlichiosis was only examined here in the context of infection with highly virulent E. japonica species that cause lethal infection in mice." (PMID 38022511, 2023). "For Toll signaling pathway-related genes, the expression of the Toll9, TNF receptor associated factor 6 (TRAF6), Myd88, and Pellino genes was upregulated in R. chinensis after infection with SM1, while the expression of Spatzle was downregulated in this study." (PMID 35323524, 2022). "Infection experiments were performed using homozygous C57BL/6J-derived MyD88 (-/-) knock-out (MyD88 KO) mice deficient in signaling of all TLRs through the MyD88 adaptor and retaining only the TRIF-mediated endosomal TLR4 and TLR3 signaling pathways." (PMID 35395059, 2022). "As most TLRs recruit general adaptor protein MyD88 to activate NF-κB, infection of MyD88-deficient macrophages, as compared to wild-type macrophages, with R-LD leads to a remarkable greater amastigote numbers accompanied by elevated IL-10/IL-12 ratio." (PMID 35925884, 2022). "MyD88‐/‐ C57BL/6 infected with L. major LV39 strains susceptible to infection is due to impaired Th1 response." (PMID 35119120, 2022). "Cytokine elaboration likely underlies the MyD88-driven host control of bacterial burdens in disparate infection sites, even when different upstream receptors are required for activation." (PMID 36226943, 2022). "Genetic deficiency of MyD88 in Ifitm3−/− mice resolved infection-induced weight loss to wt levels, indicating that signalling through MyD88 is required to drive exacerbated weight loss in Ifitm3−/− mice." (PMID 36075894, 2022). "Association of TLRs and MyD88-mediated pathway during infection by Leishmania was first studied in 2002, reporting decreased IL-1α expression in MyD88−/− mice upon infection by L. major." (PMID 35531875, 2022). "The number of leukocytes at the site of infection was significantly lower in the Myd88-deficient larvae." (PMID 33559740, 2021). "Studies have shown that the TLR2 and MyD88 pathways play an important role in bone loss caused by infection." (PMID 33461495, 2021). "Using electron microscopy, we showed that the majority of bacteria in Myd88-deficient larvae were located extracellularly, most likely as a result of the reduced number of phagocytes present at the site of infection." (PMID 33559740, 2021).
infection (continued). "In this context, CYLD was shown to target K63-linked ubiquitin chains on MYD88, which are induced by infection with Haemophilus influenzae (NTHi) in vitro and in vivo." (PMID 33808506, 2021). "The relatively narrow susceptibility to infection in humans contrasts with MyD88-deficient mice, which are much more broadly vulnerable to bacterial, viral, fungal and parasitic infections under experimental conditions." (PMID 34199501, 2021). "Neu1-overexpression and siglec-E-silencing together followed by infection activated both MyD88 and TRIF-signaling through their enhanced TLR4-association." (PMID 33763070, 2021). "Animals deficient of TRIF and MyD88 infected with T. cruzi are more susceptible to infection, with higher parasitism and low macrophage activation, resulting in a low production of nitric oxide." (PMID 34336720, 2021). "It appears that small molecules which target TIR domain interactions in MyD88‐dependent TLR signaling represent a promising strategy toward host‐directed therapeutics against infection‐induced inflammation-associated sepsis." (PMID 33834387, 2021). "As a result, deficiency in Myd88-dependent signalling leads to an increased infection due to uncontrolled, mainly extracellular, mycobacterial growth." (PMID 33559740, 2021). "Overexpression of CYLD in cells decreased K63-ubiquitination levels, whereas its knock-down increased K63-linked ubiquitination of MYD88 upon infection with NTHi." (PMID 33808506, 2021). "We used qPCR to measure the gene expression of the NF-κB–activated genes IL-8 and IL-6 as well as the interferon-stimulated genes (ISGs) IFIT1 and IFIT2 in MyD88-deficient cells and MyD88-intact cells during DENV2 infection." (PMID 32117091, 2020). "Although IL-1β/MyD88 deficiency in Tregs is a common link in poor infection outcomes in our MFYcre and aging infection models, there are distinct differences between them." (PMID 33240286, 2020). "Defects in TLR-activated signaling pathways, including deficiency in the adaptor protein myeloid differentiation factor 88 (MyD88), are associated with markedly increased susceptibility to infection." (PMID 32209688, 2020). "Notable exceptions include several CD4+ T cell-associated genes (including HPGDS and MYD88), which were transiently upregulated during the ramp-up and peak stages of infection." (PMID 32119719, 2020). "The index patient of a MyD88-deficient kindred II.2 suffered from multiple pyogenic infections in infancy, ultimately leading to genetic workup of a suspected TLR signaling defect." (PMID 33424861, 2020). "A study performed using the B. burgdorferi model of infection in a T cell-specific MyD88 deletion model demonstrated that loss of MyD88 in T cells results in an intrinsic defect in the Th1 and Th17 response." (PMID 32582209, 2020). "In contrast, infections with S. aureus are a primary indicator of a deficiency in cellular innate immunity, that is MyD88/IRAK4 deficiency and chronic granulomatous disease." (PMID 32639232, 2020). "The role of MyD88 signaling in innate immunity is highlighted by high incidence of life-threatening infection in patients with MyD88 and IRAK4 deficiencies." (PMID 33679711, 2020). "MyD88−/− mice, for example, fail to mount adaptive immune responses against Listeria monocytogenes and are therefore highly susceptible to infection." (PMID 33584721, 2020). "The same study also demonstrated that MyD88-deficient mice have a more dramatic increase in bacterial burden than Tlr2 knockouts after intratracheal infection with virulent C. burnetii Nine Mile phase I." (PMID 30800124, 2019).